INS (insulin)
Diseases named in the same sentence as INS in open-access papers (continued):
Sharing a sentence is not in itself a finding about the gene and the disease.
diabetes (continued). "A family member's serious illness was the only childhood adversity which statistically significantly increased the risk of belonging to the insulin-managed diabetes group even when confounding factors were included (OR 1.89, 95% CI 1.17–3.04)." (PMID 24868461, 2014). "Hepatic TG accumulation causes acquired insulin-signaling defects (probably via Fetuin-A) and subsequent IR, glucose intolerance and Type 2 diabetes mellitus." (PMID 24829591, 2014). "Some plausible mechanisms have been proposed for the link between low cardiorespiratory fitness and diabetes risk; for example, the fact that individuals with low cardiorespiratory fitness tend to have low insulin sensitivity." (PMID 24885699, 2014). "In models adjusted for 2-hour insulin, the T allele was associated with lower prevalent diabetes risk (odds ratio 0.56 (95% CI 0.31–0.95))." (PMID 25197274, 2014). "Diabetes is a debilitating disease characterized by deficiencies in insulin secretion, insulin action, or both, leading to chronic hyperglycaemia." (PMID 25424627, 2014). "Evidence from a number of other observational studies shows that certain dietary constituents are associated with protection against diabetes through the pathway of insulin sensitivity which is also confirmed through food trials." (PMID 25192735, 2014). "Links between complement component 3 (C3) and acylation stimulating protein (ASP) with diabetes and well-recognized risk factors such as lipids and glucose/insulin have already been studied in detail." (PMID 25275325, 2014). "Similar to our findings, studies done in other countries have shown insulin use further increases the risk of fragility fractures in individuals with diabetes, perhaps by acting as a marker of disease severity." (PMID 24919660, 2014). "As TXNDC5 helps in correct insulin folding, when its concentration decreases in pancreatic islets, the amount of insulin is reduced, causing diabetes, so TXNDC5 has a central role in glucose toxicity." (PMID 25526565, 2014). "Diabetes in ZDF rats is known to progress from a stage of severe hyperinsulinemia to progressive insulin loss and finally to insulinopenia by the time they are 24 weeks of age." (PMID 25062042, 2014). "In type 1 diabetes mellitus, pancreatic islet inflammation contributes to the progressive loss of insulin producing β cells and inflammatory mediators, e.g., IL-1β, TNF-α, and IFN-γ contribute to the suppression of β cell function and subsequent apoptosis." (PMID 24366643, 2014). "The present model of diabetes was associated with decreased serum insulin and increased blood glucose." (PMID 24644382, 2014). "Deficient insulin secretion, resulting in chronically elevated blood glucose levels, is a characteristic of diabetes mellitus." (PMID 25375650, 2014). "The heterozygous GLUT4+/− mice, however, suffered from insulin resistant and were predisposed to develop into diabetes." (PMID 25258641, 2014). "FoxC2 polymorphisms and abnormal protein expression have been implicated with insulin sensitivity in patients with obesity and diabetes mellitus." (PMID 24608096, 2014). "An important message of this study is the demonstration that relatively modest fat mass loss achieved by most black women improved insulin sensitivity in a population that is at high risk of developing diabetes and associated complications." (PMID 25110634, 2014). "Diabetes mellitus is a syndrome characterized by chronic hyperglycemia and associated with absolute or relative deficiency in insulin secretion or insulin action." (PMID 24729889, 2014). "T1DM is often characterised by weight loss prior to diagnosis of diabetes and weight gain following initiation of insulin therapy." (PMID 24885742, 2014). "The majority of reported loci that predispose to diabetes seem to act through insulin secretion defects from pancreatic islets." (PMID 25375650, 2014).
diabetes (continued). "Approximately half of the individuals with essential hypertension are insulin resistant; however, diabetes is typically considered to be the risk factor for cardiovascular disease." (PMID 26167199, 2014). "Patients with established diabetes receiving insulin are at particularly high risk of major adverse events which should be considered in decisions about surgical interventions." (PMID 25361884, 2014). "Fetuin-A, a liver-derived glycoprotein that impairs insulin-signalling, hasemerged as a biomarker for diabetes risk." (PMID 24548643, 2014). "Considering inflammatory function of insulin, previous studies have shown a strong association between obesity and diabetes." (PMID 24884617, 2014). "Diabetes is a metabolic disorder that causes an increase in the production of serum glucose due to the body’s inability to provide adequate quantities of insulin." (PMID 24576381, 2014). "One of the most striking effects of TAD was the significant improvement in insulin sensitivity (decreased insulin AUC), and improvement in glucose metabolism (decreased glucose AUC) observed among AA with high risk for diabetes." (PMID 25226279, 2014). "It usually presents in childhood, accounts for 5–10% of all diabetes, and is associated with the presence of islet-cell antibodies, and patients require lifelong insulin treatment." (PMID 24409188, 2014). "Diabetes is caused by the autoimmune destruction of pancreatic β cells (i.e., type 1 diabetes) or the combination of insulin resistance of all body organs and insulin secretion deficiency (i.e., type 2 diabetes)." (PMID 24743240, 2014). "Insulin resistance, or the impaired ability of insulin to mediate glucose disposal, is a risk factor for several disorders including the metabolic syndrome, type 2 diabetes mellitus, gestational diabetes, cardiovascular disease and several forms of cancer." (PMID 25259572, 2014). "The size of mature islets and the number of insulin-producing cells they contain are critical determinants of pancreatic postnatal function and the risk of developing diabetes." (PMID 25082160, 2014). "Targeted knockdown of Drosophila orthologues of diabetes risk genes revealed tissue-specific roles for these genes in regulating insulin production and secretion." (PMID 25101872, 2014). "Diabetes-related factors associated included use of insulin (OR 2.62, 95% CI: 1.67-4.13) and oral glucose-lowering agents (OR 1.81, 95% CI: 1.33-2.45)." (PMID 25514968, 2014). "The researchers measured the body composition of the study participants and the levels of insulin, glucose, and other markers of diabetes risk in fasting blood samples (blood taken from the children 8–10 hours after their last meal or drink)." (PMID 25181492, 2014). "It is important to mention that the insulin treatment is demonstrated to prevent or correct the axonal atrophy caused by STZ-diabetes in the large myelinated fibers as well as the axonal diameter and their distributions." (PMID 24387617, 2014). "There were no between group differences in fasting blood glucose, postprandial blood glucose, insulin resistance or any other factors related to diabetes risk or psychological well-being." (PMID 24980650, 2014). "Diabetes mellitus type 2 is associated with insulin resistance, elevated insulin levels and an increased risk of cancer and cancer-related mortality." (PMID 24612549, 2014). "This family background is associated with an increase in fasting insulin levels (OR 1.7), a decrease in insulin sensibility (OR 1.95), and an increase in the risk of diabetes (OR 1.63)." (PMID 24935278, 2014). "People affected by type 1 diabetes mellitus (T1DM; the insulin-deficient form of diabetes) or type 2 diabetes mellitus (T2DM; the insulin-resistant form of diabetes) have significantly reduced life expectancy compared to normal individuals." (PMID 24589844, 2014).
diabetes (continued). "In the experimental model, rotavirus infection caused inflammation of the insulin producing cells and induction of diabetes, which was attributed to β-cell autoimmunity." (PMID 25574400, 2014). "Of interest, 2-aminoadipate was decreased by eNOS and this metabolite has been shown to be a biomarker for diabetes risk and to regulate insulin and glucose homeostasis." (PMID 25505420, 2014). "Diabetes is a disorder of energy metabolism caused by inadequate insulin action, either quantitatively or qualitatively." (PMID 24886453, 2014). "Towards diabetes diagnosis this group experienced a pattern of beta cell compensation followed by loss of beta cell function, whereas insulin resistance only increased slightly." (PMID 24523667, 2014). "Glucagon-like peptide-1 (GLP-1) and glucose-dependent insulinotropic polypeptide (GIP) are important regulators of insulin secretion, and their functional loss is an early characteristic of type 2 diabetes mellitus (T2DM)." (PMID 25191754, 2014). "In type 2 diabetes mellitus, the resistance to insulin is assumed to be caused by changes in the abundance of the AS isoforms of insulin receptor." (PMID 25988147, 2014). "In streptozotocin models of diabetes, due to the destruction of pancreatic beta-cells, insulin secretion has been impaired and cause blood glucose elevation." (PMID 25184241, 2014). "Diabetes mellitus is a chronic disease resulting from a relative or absolute deficiency of insulin, which affects the metabolism of carbohydrate, protein, and fat." (PMID 26464864, 2014). "Intracellular ceramide accumulation predisposes individuals to development of diabetes by impairment of insulin responsiveness." (PMID 24701589, 2014). "Peripheral artery disease patients with diabetes requiring insulin are at high risk of intermediate term mortality." (PMID 25361884, 2014). "Although diabetes requiring insulin therapy was a significant risk factor, the major risk factors relate to technical aspects of surgery, particularly synchronous bowel procedures." (PMID 25202167, 2014). "Detection bias and reverse causality surrounding the diabetes diagnosis and insulin initiation were addressed by these protocol driven measures." (PMID 24667573, 2014). "A study among older adults with diabetes showed that HbA1C <6% was related with greater risk of falls but only in those treated with insulin therapy." (PMID 25140176, 2014). "The Reg gene family consists of five clustered genes mapped to a locus linked to altered insulin secretion and encoding proteins associated with pancreatitis, diabetes, β-cell damage, β-cell replication and islet neogenesis." (PMID 24587207, 2014). "In diabetes the associated hyperglycemia, obesity and insulin changes highly accelerate the progression to atherosclerosis." (PMID 24918095, 2014). "Diabetes mellitus is a common metabolic disorder characterized by absolute or relative deficiencies in insulin secretion and/or insulin action associated with chronic hyperglycemia and disturbances of carbohydrate, lipid and protein metabolism." (PMID 25481115, 2014). "Diabetes, as a complex metabolic disorder caused by insulin insufficiency and/or insulin dysfunction, is characterized by aberrant blood glucose and insulin levels." (PMID 25351676, 2014). "Hyperinsulinemia, a high level of blood insulin, is often associated with impaired physiological conditions such as hypoglycemia, insulin resistance, and diabetes." (PMID 24795642, 2014). "Insulin helps fat and muscle cells absorb glucose from the blood, and so diabetes can result in high levels of blood glucose, which can cause strokes, blindness, and heart disease." (PMID 25233132, 2014). "Insulin therapy reduces microvascular risk in T1DM patients (Writing Team for the Diabetes Control and Complications Trial/Epidemiology of Diabetes Interventions and Complications Research Group, 2002)." (PMID 25364717, 2014).
diabetes (continued). "Inconsistencies in reports of the effects of LXR activation on whole-body insulin sensitivity has raised concerns about the possibility of increased diabetes associated with as an anti-atherosclerosis target." (PMID 24972069, 2014). "Alloxan-induced diabetes consistently produced the main characteristics of diabetes mellitus including polydipsia, polyphagia, polyuria, decreased insulin levels, weight loss and hyperglycemia." (PMID 24891878, 2014). "We applied clinical criteria derived from the literature to establish 1) definite diabetes, 2) diabetes initially severe-requiring treatment with insulin, 3) remission of diabetes, and 4) exclusion of known causes of remitting diabetes." (PMID 24909320, 2014). "Type 1 diabetes mellitus (T1DM) is an autoimmune disease caused by immune-mediated destruction of insulin-secreting β cells of the pancreas." (PMID 24594640, 2014). "In middle-aged women, IGFBP1 levels rose after the onset of diabetes, indicating a loss of insulin sensitivity in the liver." (PMID 23781317, 2013). "T1D is a T cell-mediated autoimmune disease that results from a selective destruction of the pancreatic insulin-producing β-cells and is the most common cause of diabetes in children, accounting for over 95% of cases." (PMID 24051999, 2013). "The case presented here suggests that a heterozygous INS mutation which disrupts the HCR can cause severe insulin deficiency with very early onset of diabetes and in utero growth retardation." (PMID 23350652, 2013). "Progressive weight gain associated with insulin therapy is a major challenge for diabetes patients, particularly those with obesity." (PMID 23061470, 2013). "Although we attempted to explore glucose and insulin as mediators in the causal pathway of incident diabetes, our only lactate sample was measured at the same time as glucose and insulin." (PMID 23383072, 2013). "Diabetes mellitus is a syndrome associated with a disordered metabolism and inappropriate hyperglycemia that can be due to either an absolute deficiency in insulin secretion or reduction in the biological effectiveness of insulin." (PMID 23983807, 2013). "Diabetes-induced heart dysfunction is associated with a very low plasma insulin level, and an unbalanced level of oxidative stress to antioxidant defense ratio, while oxidative stress in diabetic animals is reversed with antioxidants." (PMID 23923043, 2013). "Diabetes is a metabolic disease determined by defects in insulin secretion, insulin action, or both, which caused a chronic hyperglycemia with a long-term damage, dysfunction, and failure of different organs." (PMID 24319351, 2013). "Insulin use was significantly associated with higher communicative HL (p = 0.002), critical HL (p = 0.017), and understanding of diabetes care (p < 0.001)." (PMID 23522359, 2013). "This is followed by an overt, insulin deficient diabetes phase that is distinguished by destruction of the majority of β-cell." (PMID 24279645, 2013). "High circulating levels of insulin and IGFs are associated with obesity and diabetes; in the female reproductive system, increased levels of these growth factors are associated with polycystic ovary syndrome (PCOS) and ovarian cancer." (PMID 23388061, 2013). "There is increasing evidence for a cause-effect link between environmental toxicants and diabetes that is related to adipose tissue accumulation and reported effects on insulin production/resistance." (PMID 23289729, 2013). "Deficiency of PICK1 or ICA69 in mice led to diabetes-like phenotypes characterized by glucose intolerance, insufficient insulin release, and elevated proinsulin secretion." (PMID 23630453, 2013). "This increase in age-related fat accumulation in humans and rodents is mainly attributed to altered insulin sensitivity, which is a major risk factor for obesity, diabetes and atherosclerosis." (PMID 23516615, 2013).
diabetes (continued). "Of those diagnosed with diabetes, approximately 5–10% have type 1 diabetes, which is characterized by the loss of insulin production in pancreatic beta-cells, whereas 90–95% have type 2 diabetes, which is characterized by insulin resistance." (PMID 23690860, 2013). "Cognitive impairments associated with diabetes mellitus caused by inadequate insulin/insulin receptor functions in brain have been documented." (PMID 23638297, 2013). "Further study of risk factors for hypoglycaemia in non-insulin-treated diabetes is required to develop procedures and policies to limit hypoglycaemia and accident risk in this population." (PMID 23121373, 2013). "Diabetes mellitus, a metabolic disorder caused by an absolute or relative deficiency of insulin, is a debilitating and costly disease with multiple serious complications." (PMID 24171152, 2013). "Insulin use and diabetes complications were significantly associated with lower ADDQoL scores, similar to our findings on the same patient group." (PMID 24349036, 2013). "In this study, diabetes in rats was mimicked by intraperitoneal injection of STZ which selectively causes damage to islet beta cells to suppress insulin secretion." (PMID 24180212, 2013). "Type 1 diabetes mellitus (T1DM) is caused by immune destruction of insulin-producing pancreatic β-cells." (PMID 23826312, 2013). "Impaired insulin signaling and glucose intolerance, hallmarks of diabetes, are implicated in Parkinson's disease." (PMID 24376773, 2013). "Diabetes develops due to a deficiency in circulating insulin caused by pancreatic β-cell destruction and/or impaired β-cell function." (PMID 24250814, 2013). "Leptin is an adipocyte-specific ob gene product that has been found to be associated with insulin resistance and diabetes in obesity patients through insulin sensitivity and insulin secretion alterations." (PMID 24282409, 2013). "Type 2 diabetes mellitus (T2DM) is the most common form of diabetes characterized by hyperglycemia, which is caused by impairment in both insulin secretion and action." (PMID 23577093, 2013). "Among the covariates, insulin use was consistently associated with higher understanding of diabetes care (p < 0.001) in models including any of the subscales of HL." (PMID 23522359, 2013). "Further, insulin sensitivity is improved both acutely after a single bout of exercise and shows chronic effects with exercise training, effectively reducing diabetes risk." (PMID 24772374, 2013). "Diabetes mellitus is defined as a group of metabolic diseases that are associated with the presence of a hyperglycemic state due to impairments in insulin release and/or function." (PMID 24391596, 2013). "Obesity induces an insulin-resistant state in adipose tissue, liver, and muscle and is a strong risk factor for the development of type 2 diabetes mellitus." (PMID 23431246, 2013). "Several previous studies have examined the associations of BMD with obesity, diabetes, insulin resistance, and serum insulin levels." (PMID 24358252, 2013). "– Substitutive; the drug replaces a deficient natural constituent in the organism (e.g. insulin for diabetics)." (PMID 23331768, 2013). "To better understand the role of insulin resistance and diabetes on gender differences, we compared CVD risk factors between men and women with similar states of insulin sensitivity, insulin resistance or overt diabetes." (PMID 23341938, 2013). "It is commonly believed that some kind of pancreatic “exhaustion” underlies the eventual insulin secretion failure and the emergence of the frank picture of diabetes mellitus in the final stages of the pathogenesis of T2DM." (PMID 24009656, 2013). "Class I contains the isoforms associated with insulin-stimulated regulation of glucose metabolism, and has been historically the pathway of interest in diabetes research." (PMID 23516411, 2013).